GFAP (glial fibrillary acidic protein)
Diseases named in the same sentence as GFAP in open-access papers (continued):
Sharing a sentence is not in itself a finding about the gene and the disease.
axonal neuropathy (1 paper, 2024). Any nerve disorder affecting the axon of a nerve. "The activation of GFAP and protein induction plays a crucial role in astrogliosis after a nerve injury and axonal degeneration in non-myelinating Schwann cells, as characterized by an increased GFAP expression in an axonal neuropathy." (PMID 39431272, 2024).
B cell deficiency (1 paper, 2016). A broad classification of disorders where circulating numbers of B lymphocytes are decreased or ineffective. "To address whether astrocyte proliferation is affected by B cell deficiency, we examined expression of the astrocyte marker, GFAP, in the brain of JhD/MRL/lpr and hCD20-DTA/MRL/lpr mice." (PMID 27055816, 2016).
Blindness (1 paper, 2023). Blindness is the condition of lacking visual perception defined as a profound reduction in visual perception. "Inflammation and angiogenic mediators lead to a stress response in retinal glial cells characterized by enhanced production of glial fibrillary acidic protein (GFAP), and impaired function or death of photoreceptor cells, which may ultimately lead to blindness." (PMID 38115006, 2023).
blood pressure (1 paper, 2023). "This may be used to introduce very early treatment in the prehospital setting such as hemostatic therapy or lowering of high blood pressure due to the 100% specificity of GFAP to exclude other diagnoses (e.g., AIS)." (PMID 36604741, 2023).
bone marrow cancer (1 paper, 2021). "Song and co-workers found that minocycline prevented astrocyte gliosis (GFAP upregulation) in a rat model of bone marrow cancer-induced allodynia." (PMID 34446062, 2021).
breast adenocarcinoma (1 paper, 2017). "We also selected a metastasis of a breast adenocarcinoma in the posterior fossa for study which immunohistochemically showed expression of GFAP and S100, so it was misleading for the diagnosis of carcinoma." (PMID 28638988, 2017).
breast invasive carcinoma (1 paper, 2023). "Results from the survival analysis showed that the up-regulated genes AKT3 and VDAC1 and the down-regulated genes ADCYAP1R1, GFAP, and C4A were found to be significantly associated with the overall survival of the patients with breast invasive carcinoma." (PMID 37834358, 2023). "We found that the FTD DEGs, AKT3, UBE2N, VDAC1, ADCYAP1R1, C4A, and GFAP showed significant comorbidity in breast invasive carcinoma patients at a p-value < 0.05." (PMID 37834358, 2023).
breast tumor (1 paper, 2025). "The most significant variation of BRCA1 expression was obtained in contact with the GFAP + PTX scaffold (p < 0.01), suggesting that the composition of GFAP promotes PTX activity with the highest efficiency in breast tumor cells." (PMID 39940603, 2025). "The results obtained in this study indicated a time-dependent increase in ROS generation in breast tumor cells exposed to PTX-containing scaffolds, the highest increase being recorded for the GFAP + PTX scaffold, suggesting the ability of this composition to sustain the PTX effect." (PMID 39940603, 2025).
CADASIL (1 paper, 2024). "In the study of Chen containing 63 CADASIL patients, they found that plasma GFAP was significantly elevated in the CADASIL patients compared with controls." (PMID 38216970, 2024).
capillary hemangioma (1 paper, 2024). A common hemangioma characterized by the presence of capillary-sized vascular channels without prominent epithelioid endothelial cells. "Immunohistochemically, the glioependymal tissue was positive for glial fibrillary acidic protein (GFAP), and endothelial cells were positive for glucose transporter 1 (GLUT1) and the cluster of differentiation 31 (CD31), which corresponded to juvenile capillary hemangioma." (PMID 38240785, 2024).
cataract (1 paper, 2022). Partial or complete opacity of the crystalline lens of one or both eyes that decreases visual acuity and eventually results in blindness. "Notably, except for GFAP, the concentrations of all the AD-related proteins were significantly different in AH samples from nAMD and cataract patients." (PMID 36408096, 2022).
central nervous system infection (1 paper, 2023). "Therefore, when the etiology of patients suspected of having a central nervous system infection is negative, autoimmune inflammation should be considered when multiple parts of the nervous system are involved alongside empiric resistance to infection, GFAP-IgG should be tested to exclude A-GFAP-A." (PMID 36647033, 2023).
Cerebellar atrophy (1 paper, 2011). Cerebellar atrophy is defined as a cerebellum with initially normal structures, in a posterior fossa with normal size, which displays enlarged fissures (interfolial spaces) in comparison to the foliae secondary to loss of tissue. "This pronounced increase of GFAP in the molecular and granule cell layers of the cerebella of the iPLA2β-/- mice indicate that reactive astrogliosis is a characteristic feature of cerebellar atrophy in iPLA2β-/- mice." (PMID 22046428, 2011).
cerebral astrocytoma (1 paper, 2022). An astrocytoma that arises from the cerebral hemispheres. "Therefore, the conclusion of the authors was that while searching for novel therapeutic targets for cerebral astrocytomas, modulating GFAP isoforms expression and selectively splicing should be considered." (PMID 35372061, 2022).
cerebral palsy (1 paper, 2025). A group of disorders affecting the development of movement and posture, often accompanied by disturbances of sensation, perception, cognition, and behavior. "It was reported that endurance exercise (treadmill for 30 min three times a week for 4 weeks, no inclination) reduced glial fibrillary acidic protein (GFAP) expression in brain astrocytes in a rat model of cerebral palsy." (PMID 40214441, 2025).
cervical cancer (1 paper, 2023). A primary or metastatic malignant neoplasm involving the cervix. "In the co‐culture system of cervical cancer cells and SCs, signals from the cancer cells markedly enhanced the expression of GFAP, Vimentin and nestin in SCs." (PMID 37830980, 2023). "Thus, our results indicated that cervical cancer cells had a strong glial cell‐activating property that induced GFAP and Vimentin expression in SCs partially via the PACAP paracrine signalling." (PMID 37830980, 2023). "Notably, in human cervical cancer specimens with PNI, we found close associations between GFAP+ or Vimentin+ SCs and cervical cancer cells." (PMID 37830980, 2023).
chondroma (1 paper, 2022). A benign well circumscribed neoplasm of hyaline cartilage arising from bone or soft tissue. "On histopathological examination, the tumor was diagnosed as chondroma; Vimentin, S-100 and Ki-67(2%) stained positive, but EMA, CK, CK18, CD34, SOX-9 and GFAP stained negative by ICH." (PMID 35692788, 2022). "The pathological diagnosis was chondroma; ICH showed Vimentin and S-100 stain was positive, but Ki-67, CK, CK18, EMA, CD34 and GFAP stain was negative." (PMID 35692788, 2022). "On histopathological examination, the tumor was diagnosed as chondroma; Vimentin, Ki-67 (6%), SOX-9, and S-100 stained positive, but CK, CK18, EMA, CD34 and GFAP stained negative." (PMID 35692788, 2022).
Chorea (1 paper, 2025). Chorea (Greek for 'dance') refers to widespread arrhythmic involuntary movements of a forcible, jerky and restless fashion. "In the PKAN group, GFAP, Tau, and UCH-L1 demonstrated strong correlations with subscale 5, which evaluates dystonia, and GFAP and Tau also correlated with subscale 6, which includes other neurological signs such as speech, chorea, and spasticity." (PMID 41294854, 2025). "Interestingly, although GFAP concentrations were not elevated in the PKAN group, but they did correlate with NfL and Tau levels, as well as evaluations of dystonia and other neurological signs, including speech, spasticity, and chorea, suggesting it could be a biomarker of disease severity." (PMID 41294854, 2025).
chronic heart failure (1 paper, 2022). "Our group has recently shown that memory deficits in patients with chronic heart failure associate with elevated levels of serum GFAP." (PMID 36142218, 2022).
Chronic Hepatitis C Infection (1 paper, 2014). "The aim of this study was to appraise the structural characteristics and distribution of HSCs expressing both GFAP and SMA in chronic hepatitis C and to associate these markers with stages of fibrosis and necroinflammatory grades in CHC patients." (PMID 25225520, 2014).
colitis Crohn (1 paper, 2011). "Colonic parts without inflammation in patients with colitis Crohn showed a reduced labelling of GFAP and no expression of GDNF in comparison to non-inflamed gut structures of patients with UC." (PMID 21235736, 2011).
complication (1 paper, 2024). Any disease or disorder that occurs during the course of, or because of, another disease, treatment, or procedure. "The women with HELLP had more than 4-fold higher tau and greater than 1.5-fold higher neurofilament light (NfL) and GFAP compared to preeclamptic women without neurologic complications, pulmonary edema, or HELLP." (PMID 39857613, 2024).
Constipation (1 paper, 2026). Infrequent or difficult evacuation of feces. "Bifidobacterium bifidum CCFM1163 increased fecal water content and SCFA levels, improved gut microbiota composition, and reduced GFAP mRNA expression in a mouse model of induced constipation." (PMID 41486750, 2026).
Creutzfeldt-Jakob diseases (1 paper, 2013). "Generally, Aqp1 and/or Aqp9 are elevated in hypertrophied, GFAP overexpressing astrocytes in a number of pathological states, such as ischemic or traumatic brain injury, Alzheimer’s or Creutzfeldt-Jakob diseases." (PMID 23940528, 2013).
cystoid macular edema (1 paper, 2020). An autosomal dominantly inherited cystoid macular edema manifesting with macular atrophy, strabismus and, sometimes, pericentral retinitis pigmentosa. "In a severe case of cystoid macular edema (CME), GFAP and Nogo-A expression colocalized in gliotic Müller cells." (PMID 32029703, 2020).
dengue (1 paper, 2020). "The astrocyte population (GFAP+ cells) also presented with altered morphology in brain cuts from fatal dengue cases." (PMID 32486462, 2020).
dependence (1 paper, 2025). "The identification of clinically validated biomarkers (GFAP, UCHL1, CHI3L1) in the dependence group suggests potential for developing diagnostic and monitoring tools for alcohol-related brain injury." (PMID 41292811, 2025).
diabetic macular edema (1 paper, 2025). "Although we did not perform immunohistochemical analysis of glial fibrillary acidic protein expression in the retina, we believe that VA therapy may serve as an alternative or adjunctive therapy for diabetic macular edema." (PMID 41400317, 2025).
diffuse midline glioma (1 paper, 2022). A diffuse glioma that arises from the midline structures of the central nervous system. "Herein, we described an extremely rare case of diffuse midline glioma, H3-K27M mutation with GFAP-positive anucleate whorled patterns." (PMID 35713454, 2022).
dilatation (1 paper, 2012). "The ventricular dilatation were evaluated by MRI at 1-week post drugs treated, while GFAP and Iba-1were detected by RT-PCR, Immunohistochemistry and Western blot." (PMID 23217034, 2012).
Encephalocele (1 paper, 2025). A neural tube defect characterized by sac-like protrusions of the brain and the membranes that cover it through openings in the skull. "The pathology findings in the seven encephaloceles were variable; two cases showed small superficial defects on gyral crests of temporal lobe, highlighted with increased subpial GFAP labeling and a reduction of NeuN‐positive neurons." (PMID 40299318, 2025).
Epiretinal membrane (1 paper, 2018). An epiretinal membrane is a thin sheet of fibrous tissue on the surface of the retina along the inner limiting membrane. "The presence of GFAP immunostaining in both PDR and idiopathic epiretinal membranes suggests that glial cells, such as retinal Müller cells and astrocytes, are a prominent component of these membranes." (PMID 29351334, 2018). "We also compared the relative immunofluorescence of ETB with glial fibrillary acidic protein (GFAP) in both diabetic and idiopathic epiretinal membranes in an effort to further characterize their potential roles in membrane formation." (PMID 29351334, 2018).
Epstein-Barr virus infection (1 paper, 2022). An infection that is caused by Epstein-Barr virus. "Anti-myelin antibodies co-occured with Herpes simplex virus (HSV)-2 IgG (p = 0.0415), anti-CV2 with HSV-1 IgM (p = 0.0394), whereas anti-glial fibrillary acidic protein was linked with past Epstein-Barr virus infection." (PMID 35624969, 2022). "Previous EBV infection appears as an important anti-GFAP antibody production factor." (PMID 35624969, 2022).
Fabry disease (1 paper, 2021). Fabry disease (FD) is a progressive, inherited, multisystemic lysosomal storage disease characterized by specific neurological, cutaneous, renal, cardiovascular, cochleo-vestibular and cerebrovascular manifestations. "Neuroinflammation, embodied by Iba1 or GFAP staining, was observed in most of the models evaluated, with the exception of Gaucher and Fabry disease mouse models." (PMID 33919140, 2021).
Failure to thrive (1 paper, 2024). Failure to thrive (FTT) refers to a child whose physical growth is substantially below the norm. "With high levels of GFAP, myelin deficiencies, and functional impairments, including motor impairment, failure to thrive, and increased mortality, the GFAP-R237H rat carries a significant pathological burden." (PMID 38920997, 2024).
fibroma (1 paper, 2024). A non-metastasizing neoplasm arising from the fibrous tissue. "The lesion showed a sclerotic fibroma/collagenoma-like storiform pattern with entrapped glial tissue that was S100 and GFAP positive." (PMID 38265101, 2024).
Friedreich ataxia (1 paper, 2025). An inherited condition that affects the nervous system and causes movement problems. "GFAP concentrations in biofluids have been evaluated in SCA3, SCA1, and SCA6 with no remarkable findings, although increased GFAP levels were found in plasma from Friedreich’s ataxia patients." (PMID 40507882, 2025).
functional dyspepsia (1 paper, 2025). "Our previous research also revealed that in patients with functional dyspepsia (FD), the increased expression of GFAP was positively correlated with epigastric pain symptoms." (PMID 40225339, 2025).
gastrointestinal stromal tumour (1 paper, 2008). "CD34 and CD117 were used to exclude a gastrointestinal stromal tumour, whereas GFAP expression confirmed neural differentiation." (PMID 18518995, 2008).
Gerstmann syndrome (1 paper, 2024). Gerstmann syndrome is a very rare neurological disorder characterized by the specific association of acalculia, finger agnosia, left-right disorientation, and agraphia, which is supposed to be secondary to a focal subcortical white matter damage in the parietal lobe. "In this case report, we present the 12-month clinical, radiological, and laboratory evolution of a patient with a rare case of FLAMES, positive anti-GFAP antibodies, and Gerstmann syndrome." (PMID 39479094, 2024).
gestational diabetes (1 paper, 2025). Carbohydrate intolerance first diagnosed during pregnancy. "Additionally, a significant reduction in GFAP-expressing astrocytes was observed with the progression of gestational diabetes in the STZ groups." (PMID 40243881, 2025).
Granuloma (1 paper, 2025). A compact, organized collection of mature mononuclear phagocytes, which may be but is not necessarily accompanied by accessory features such as necrosis. "Activated HSCs are typically localized at the periphery of hepatic granulomas, where they exhibit elevated expression of Desmin, α-smooth muscle actin (α-SMA), and glial fibrillary acidic protein (GFAP)." (PMID 41220567, 2025).
HCMV infection (1 paper, 2011). "HCMV infection of neural progenitor cells in the undifferentiated stage down-regulated GFAP expression while it remained unaltered following infection after differentiation." (PMID 21249143, 2011).
head and neck cancer (1 paper, 2024). A primary or metastatic malignant neoplasm affecting the head and neck. "We identified one protein for each of bladder [WAS, 0.54 (0.39–0.73)], brain [GFAP, 1.55 (1.31–1.86)], and head and neck cancers [TPP1, 1.33 (1.16–1.52)]." (PMID 38750076, 2024).
Heat Stroke (1 paper, 2025). A condition caused by the failure of body to dissipate heat in an excessively hot environment or during PHYSICAL EXERTION in a hot environment. "Currently, several neurobiomarkers, including neuron-specific enolase (NSE), S-100 calcium-binding protein B (S-100 B), glial fibrillary acidic protein, and tau protein, are known to significantly increase in patients with heat stroke." (PMID 40433615, 2025).
hypogonadotropic hypogonadism (1 paper, 2022). Abnormal ovarian or testicular function due to insufficient hormonal stimulation from the hypothalamic-pituitary axis. "In particular, they show that the elimination of GFAP-expressing tanycytes severely impairs the activity and function of GnRH neurons leading to hypogonadotropic hypogonadism and alters sexual behaviors in male mice, highlighting their key role in the control of reproduction." (PMID 35370973, 2022).
hypothyroidism (1 paper, 2015). Abnormally low levels of thyroid hormone. "Expression alterations of genes using hypothyroidism model rats showed that immature astrocytes immunoreactive for vimentin and glial fibrillary acidic protein (GFAP) were increased, while oligodendrocyte lineage transcription factor 2 were decreased in the corpus callosum." (PMID 26089777, 2015).
ileitis (1 paper, 2017). "As a matter of fact, we observed increases in GFAP- and S100β-immunoreactivities in TNBS-induced ileitis suggesting that the inflammatory insult may stimulate enteric glial cells proliferation and/or activate the expression/synthesis of glial protein cell markers." (PMID 29167643, 2017).
irritable bowel syndrome (1 paper, 2025). Irritable bowel syndrome (IBS) is a chronic functional condition of the lower gastrointestinal (GI) tract characterized by abdominal pain or discomfort and disordered bowel habit (diarrhea, constipation, or fluctuation between the two). "And compared to control rats and enteric glial cells, the expression levels of GFAP, S100B, SP, CGRP, TRPV1, TNF, IL-1β, and IL-6, were significantly higher in the colonic tissues of irritable bowel syndrome (IBS) rats and lipopolysaccharide (LPS)-treated EGCs." (PMID 40225339, 2025).
learning disabilities (1 paper, 2020). "Hence, one possibility is that in 16-week-old Ngsk mutants, improved LTD due to increased GFAP may have had a milder impact on the motor learning disabilities." (PMID 32985542, 2020).
Leber congenital amaurosis (1 paper, 2016). Leber congenital amaurosis (LCA) is a retinal dystrophy defined by blindness and responses to electrophysiological stimulation (Ganzfeld electroretinogram (ERG)) below threshold, associated with severe visual impairment within the first year of life. "Immunohistochemical assays of the epithelial membrane antigen (EMA), S100, vimentin, KI67, creatine kinase (CK), Leber congenital amaurosis (LCA), CD68, antibodies against glial fibrillary acidic protein (GFAP), BCL2, anaplastic lymphoma kinase (ALK), and synaptophysin levels were performed." (PMID 27917338, 2016).
left ventricular hypertrophy (1 paper, 2023). Enlargement of the LEFT VENTRICLE of the heart. "Notably, the significance of cardiac left ventricular hypertrophy was reaffirmed using two complementary techniques: cardiac CT scans and GFAP immunoreactivity assessment in the intrinsic cardiac ganglia (ICG) zone." (PMID 37775558, 2023).